IL6 (interleukin 6)
Diseases named in the same sentence as IL6 in open-access papers (continued):
Sharing a sentence is not in itself a finding about the gene and the disease.
injury (continued). "Knockdown of MALAT1 upregulates NF-κB and IL-6 expression in renal ischemia-reperfusion injury, but also inhibits IL-1β, IL-6 and TNF-ɑ production in Lipopolysaccharide (LPS)-induced acute lung injury, suggesting a duel function of this lncRNA in inflammatory regulation." (PMID 36052163, 2022). "Results of the present study were similar to our prior study, which showed that LPS-induced acute lung injury mice administered Sanghuangporus sanghuang mycelium could significantly decrease concentrations of TNF-α, IL-1β, IL-6, and NO in bronchoalveolar lavage." (PMID 35111796, 2021). "Interestingly, repeated intrathecal administration of both antagonists decreased the mRNA and/or protein levels of pronociceptive interleukins (i.e., IL-1beta, IL-6, IL-18) in the spinal cord, but only (±)-NBI-74330 decreased their levels in the dorsal root ganglia after nerve injury." (PMID 34681732, 2021). "For example, STAT3 activation by IL-6 potentiates proinflammatory responses in peritoneal macrophages, whereas STAT3 activation by IL-10 dampens lipopolysaccharide (LPS)-induced inflammatory responses in Kupffer cells, and STAT3 activation by IL-22 ameliorates ethanol-induced liver injury." (PMID 31931878, 2020). "Serum from trauma patients contains other mediators beside CC16, which may change the migratory behavior of monocytes, thus further mediators such as IL-6 or RANTES that potentially increase the migratory capacity of monocytes are probably concurrently present in the blood from trauma patients." (PMID 31632392, 2019). "Other examples include Campath H-1 targeting CD52 on lymphocytes and monocytes with resulting elevated levels of TNF-α, IFN- ү, and IL-6; rituximab (anti-CD20) resulting in rapid increases in TNF-α and IL-6; and visilizumab (anti-CD3) induced cytokine release syndrome resulting in liver injury." (PMID 30469350, 2018). "Serum IL-6 levels in orthopedic injury patients without diagnosis of brain injury." (PMID 20222971, 2010). "In a mouse model of non-infectious acute lung injury, we recently demonstrated that systemic IL-6 inhibition reverses delirium-like neuronal changes in the frontal cortex and hippocampus, suggesting a key role for IL-6 in mediating delirium-like structural phenotypes." (PMID 34711238, 2021). "White blood cell (WBC), Neutrophil, Ferritin, D-dimer, Troponin, CRP, SII, interleukin-6 IL-6, AST, ALT and LDH levels were higher in patients with liver injury compared to pregnant women without liver injury." (PMID 38356834, 2024). "Additionally, cervical vagotomy significantly reduced LPS (5 mg/kg)-induced hypo-locomotion and plasma IL-6 levels, whereas neither cervical vagotomy nor SDV affected LPS-induced lung injury." (PMID 40028232, 2025). "The ISS is correlated with adrenaline, interleukin (IL)-6, histone-complexed DNA fragments, high-mobility group box 1 (HMGB1), soluble thrombomodulin (sTM) and protein C in trauma patients with high serum SDC-1 levels (≥ 63 ng/ml) but not in those with low SDC-1 levels (< 63 ng/ml)." (PMID 36237551, 2022). "Although increases in interleukin (IL)-6, IL-8, IL-10 and glial fibrillary acidic protein (GFAP) were observed in FGR infants with brain injury, it is not clear whether similar increases would be observed in cases of more subtle brain injury in FGR infants that are not currently detectable at birth." (PMID 38966491, 2024).
Cerebral ischemia (252 papers, 2009 to 2026). Restriction of arterial blood supply to the brain associated with insufficient oxygenation to support the metabolic requirements of the tissue. "Excessive ROS following cerebral ischemia/reperfusion not only directly cause cell injury but also activate numerous inflammatory cytokines, including IL-6 and IL-1β, which are released rapidly." (PMID 40527853, 2025). "It has been shown that memory deficits after acute brain ischemia are associated with increased levels of pro-inflammatory cytokines (IL-1, IL-6 and TNF-α) in the brain and neurodegeneration." (PMID 40305179, 2025). "Modern research shows that NF-κB is activated, leading to the excessive production of proinflammatory cytokines, including TNF-α, IL-1β, and IL-6, and inducible nitric oxide synthase, which cause inflammatory injury on the basis of cerebral ischemia." (PMID 35463086, 2022). "Cerebral ischemia also increased NF-κB, which causes the expression of IL-1, IL-6, and TNF genes that participate in brain damage." (PMID 33643574, 2021). "In rodent studies, cerebral ischemia causes an elevated expression of IL-6 in the injured brain and blood concentration." (PMID 34943061, 2021). "Cerebral ischemia is followed by an inflammatory reaction, the release of various proinflammatory cytokines, including IL-6, IL-1β and TNF-α, is the main mechanism underlying ischemic inflammatory injury." (PMID 32518214, 2020). "Following cerebral ischemia and reperfusion, many proinflammatory and cytotoxic factors, including IL-6, IL-1β, TNF-α, and NO, can cause cell injury and apoptosis." (PMID 30949500, 2019). "In particular, increased IL-1β, IL-6, and TNFα concentrations were linked to a poor prognosis in infants suffering from ischemic encephalopathy." (PMID 27565558, 2016). "Consistent with the well established induction of pro-inflammatory cytokines by cerebral ischemia, HI produced a marked elevation of mRNAs encoding TNFα, IL-1β and IL-6 (Veh-HI)." (PMID 23251498, 2012). "Here, we report that MCP-1-deficiency impairs the induction of IL-6, IL-1β and partially G-CSF early after cerebral ischemia, resulting in a reduced influx of neutrophil granulocytes and T-cells." (PMID 22031820, 2011). "In the present study, we propose that IL-6 could also predict mortality even at later time-points, being associated with increased risk of mortality 5 years after cerebral ischemia." (PMID 33578805, 2021). "IL6 is involved inthe induction of acute reactions and control the inflammatory responses causing areduction in pro-inflammatory cytokines and an increase in anti-inflammatorymolecules during acute cerebral ischemia stage." (PMID 31435616, 2019). "After cerebral ischemia, the dying neurons release damage-associated molecular patterns (DAMPs), which bind to the pattern recognition receptors (PPRs) in the membrane of microglia, leading to the activation of microglia and the overproduction of pro-inflammatory cytokines, such as IL-6 and iNOS." (PMID 37333874, 2023). "For instance, STAT3 has been shown to mediate endogenous IL-6 to prevent apoptosis of neurons in the acute phase of cerebral ischemia." (PMID 40313716, 2025). "Corroborating these insights, our research unveiled heightened TNF-α, IL-1β, and IL-6 concentrations in hippocampal and prefrontal cortical tissues post-cerebral ischemia." (PMID 40144659, 2025). "Tangeretin exhibits potent anti-inflammatory properties by reducing proinflammatory cytokines, TNF-α and IL-6, in rats exposed to cerebral ischemia and murine macrophage RAW264.7 cells." (PMID 40141836, 2025). "This activation releases numerous pro-inflammatory mediators and chemokines, including IL-6 and TNF-α, which play a role in neuronal death associated with cerebral ischemia and worsen the condition." (PMID 39996714, 2025). "PTGS2 and IL6, along with their receptors, primarily promote the inflammatory response following cerebral ischemia." (PMID 39847586, 2025).
Cerebral ischemia (continued). "Cerebral ischemia and hypoxia can trigger the NF-κB/interleukin (IL)-6 pathway, resulting in rapid release of IL-6." (PMID 38587684, 2024). "Cerebral ischemia and hypoxia injury can stimulate monocytes to generate interleukin-6 (IL-6), tumor necrosis factor (TNF), and other inflammatory mediators, which further aggravate cerebral ischemia and hypoxia." (PMID 39634770, 2024). "Cerebral ischemia resulted in significantly increased levels of IL-1β, IL-6, and TNF-α compared with those after sham treatment." (PMID 37812268, 2024). "In the brains of ASK1-deficient mice, decreased activation of microglia and reduced levels of TNFα, IL-6, and IL-1β were observed following brain ischemia." (PMID 39008037, 2024). "The mRNA expression of M1-related proinflammatory mediators, including IL-6, IL-1β and iNOS, was obviously and progressively increased after cerebral ischemia, reaching a peak at 24 h." (PMID 37789455, 2023). "During cerebral ischemia, the overproduction of pro-inflammatory cytokines, such as IL-6 and iNOS, was mediated by NF-κB." (PMID 37333874, 2023). "IL6 has been confirmed by several authors as a potential biomarker for delayed cerebral ischemia and inflammation following aneurysmal SAH." (PMID 37349601, 2023). "The importance of HMGB1 and other factors, including IL-6, with respect to hepcidin induction after cerebral ischemia requires further study." (PMID 37907744, 2023). "Our results demonstrated that the expression of TNF-α, IL-6, and NF-κB p65 increased after reperfusion, while the expression of IκB-α and IL-10 decreased, suggesting that cerebral ischemia triggers inflammatory response." (PMID 36970418, 2023). "Previous reports have shown that IL-6 not only mediates inflammation but also exerts a neuroprotective effect by stabilizing pericytes in the setting of cerebral ischemia." (PMID 38089883, 2023). "Studies have shown that fingolimod can attenuate the phosphorylation level of molecules in the NF‐κB pathway and decrease the inflammatory cytokines L‐1β and IL‐6 to improve neural defects and reduce neuronal damage in cerebral ischemia/reperfusion rats." (PMID 36917739, 2023). "Cerebral ischemia can cause damage to neuronal and glial cell membranes, which results in the production of TNF-α, IL-1, and IL-6." (PMID 37569457, 2023). "In experimental models of brain ischemia, IL-6 can be detected in nerve tissue as early as an hour after the middle cerebral artery (MCA) is occluded." (PMID 37342100, 2023). "Our results showed that IL-1β and IL-6 were increased in the blood of mice with brain ischemia and that valeric acid enhanced this increase." (PMID 37697393, 2023). "It has been shown that IL-6 is a critical mediator of cerebral ischemia-induced inflammatory responses." (PMID 37342100, 2023). "Brain ischemia and reperfusion increased IL-1β and IL-6 in the blood of young mice and IL-17, IL-1β, and IL6 in the blood of old mice." (PMID 37697393, 2023). "The damaged brain cells produce a large number of platelet activating factors, TNF, IL-6, and other inflammatory mediators after cerebral ischemia." (PMID 35950034, 2022). "For instance, microglial IL-6 prevents neuronal loss of neural progenitor cells during herpes simplex virus type 1 infection, and endogenous upregulation of IL-6 in response to cerebral ischemia is neuroprotective against excitotoxicity." (PMID 35250814, 2022). "Rhodiola sp. can reduce TNF-α, transforming growth factor beta 1, and IL-6 levels in the BALF in a concentration-dependent manner and inhibit inflammatory injury caused by cerebral ischemia in rats, slowing the progression of brain edema." (PMID 35432571, 2022). "During cerebral ischemia, IL-6 is produced by several sources: neurons, oligodendrocytes, astrocytes and vascular endothelial cells." (PMID 36145501, 2022).
Cerebral ischemia (continued). "One is the up-regulation of IL-6 expression after cerebral ischemia—as IL-6 regulates the JAK/STAT3 pathway to increase hepcidin content, down-regulate FPN1, and inhibit iron output—resulting in iron overload." (PMID 35481263, 2022). "Among them, interleukin 1-β (IL-1β), tumour necrosis factor-α (TNF-α) and interleukin-6 (IL-6) are expressed in the first hours after severe cerebral ischemia and participate in the increased permeability of the BBB." (PMID 36012745, 2022). "Previous studies have suggested that cerebral ischemia and hypoxia can occur through the NF-κB/IL-6 pathway, resulting in rapid IL-6 release." (PMID 36187348, 2022). "CPB triggers cerebral ischemia and hypoxia and inflammation, increasing release of inflammatory factors such as IL-1β, IL-6, TNF-α." (PMID 35526011, 2022). "We determined the effect of MLIF on cytokines which promote inflammation (IL-1 and IL-6) expression in the pathological process of brain ischemia by qRT-PCR and ELISA analysis in vivo and in vitro, respectively." (PMID 36465453, 2022). "There was an increase in MCP1, IL-1β and IL-6 in the spleen of wild-type mice and fpr1-/- mice and IL-1β and IL-6 in the brain of wild-type mice after brain ischemia." (PMID 35547761, 2022). "IL-6 and caspase-3 are two important proteins involved in the inflammation and apoptosis after cerebral ischemia." (PMID 34975719, 2021). "Taken altogether, these findings indicated the deleterious effects of IL-6 on neuronal injury after cerebral ischemia." (PMID 34943061, 2021). "Catalpol can effectively relieve cerebral ischemia-reperfusion injury, reduce inflammatory reaction, and reduce the contents of IL-1 β, IL-6, and TNF-α." (PMID 33505489, 2021). "Microglia are rapidly activated during cerebral ischemia and become key cells in the inflammatory reaction in the brain, secreting pro-inflammatory cytokines such as IL-6, IL-1β and TNF-α, which are involved in microglia-mediated neurological injury." (PMID 34504432, 2021). "It is widely reported that cerebral ischemia triggers an inflammatory response both in the brain and peripheral circulation, which leads to up-regulation of inflammatory cytokines such as IL-6." (PMID 33578805, 2021). "In our study, rats with cerebral ischemia exhibited increased IL-6 expression and Jak2 downstream Stat3 protein phosphorylation in the injured cortical tissues, livers, and gastrocnemius muscles." (PMID 34943061, 2021). "All kinds of borneol significantly reduce TNF-α levels, while D-borneol and DL-borneol reduce IL-1β levels and DL-borneol reduces IL-6 in cerebral ischemia/reperfusion models." (PMID 34017247, 2021). "Inflammation is the main pathogenesis for cerebral ischemia, and a marked inflammatory reaction is evoked by cerebral I/R with increased pro-inflammatory factors, such as TNFα, IL-1β, and IL-6." (PMID 34591125, 2021). "Glial cells, infiltrating monocytes and vascular endothelial cells also contribute to IL-6 expression after experimental cerebral ischemia." (PMID 34572077, 2021). "IL-6 is produced by neurons, oligodendrocytes, astrocytes, and vascular ECs during cerebral ischemia." (PMID 34504432, 2021). "Interleukin 6 (IL-6) is a prominent proinflammatory cytokine and has been discussed as a potential biomarker for delayed cerebral ischemia (DCI) following aneurysmal subarachnoid hemorrhage." (PMID 33420113, 2021). "The Jak2 inhibitor AG490 has been used in investigations of cerebral ischemia to explore the role of IL-6." (PMID 34943061, 2021). "In this study, the blockade of potential IL-6/Jak2 signaling was produced through the intraperitoneal introduction of AG490 30 min prior to cerebral ischemia." (PMID 34943061, 2021). "Tissues in both previous studies revealed an elevated IL-6 expression in the brain cortex, liver, and gastrocnemius of cerebral ischemia rats." (PMID 34943061, 2021).
Cerebral ischemia (continued). "The brain-related pathways demonstrated that PKall, KNG, B2KR, IL-6, TNF-α, IL-1β, LGALS-3, and PAR 2 were linked to superoxide anion generation and brain ischemia." (PMID 34867349, 2021). "IL-6 plays a comprehensive role in cerebral ischemia and is most prominently identified in neurons of peri-ischemic regions." (PMID 32518214, 2020). "A previous study reported that IL-6 has a favorable prognostic effect on cerebral ischemia and dermatological diseases because it inhibits the production of tumor necrosis factor-α and IL-1, which are classical proinflammatory cytokines." (PMID 33379208, 2020). "The results of this study showed that neuroprotective properties of IL‐6 in cerebral ischemia are mainly due to the regulation of apoptosis, cytokine secretion, and the preservation of the integrity of the blood–brain barrier." (PMID 32583980, 2020). "A previous study showed that the levels of TNF-α, IL-6, infarct volume, and cerebral edema increased in rats subjected to cerebral ischemia-reperfusion." (PMID 32153408, 2020). "Meanwhile, some studies, such as that by Suzuki and Tanaka (2009), have reported neuroprotective, antiapoptotic, and regenerative properties for IL‐6 in the setting of cerebral ischemia." (PMID 32583980, 2020). "Overall, these findings indicate that Janus kinase STAT3 pathway is activated by IL‐6, also playing a role in the regulation of cytokine secretion as well as the permeability of the blood–brain barrier in settings of cerebral ischemia." (PMID 32583980, 2020). "IL-6 is an inflammatory cytokine upregulated by cerebral ischemia, but it has also been described previously how IL-6 levels among AIS patients with previous recent TIA are lower than AIS patients without prior TIA." (PMID 33192985, 2020). "This in line with evidence that the transcription of Il6 in brain ischemia is also regulated by CREB, C/EBPβ, and AP-1, all transcription factors shown to cooperate with NF-ĸB in controlling the Il6 transcript levels." (PMID 33246465, 2020). "IL‐6 can be measured as soon as one hour following the occlusion of middle cerebral artery (MCA) in the experimental models of brain ischemia." (PMID 32583980, 2020). "Previous studies in this brain ischemia model have shown activation of astrocytes with overexpressed cytokines IL-1β or IL-6." (PMID 32501292, 2020). "Interleukin-6 (IL-6), well-known for its pro-inflammatory function also possess neurotrophic and regenerative capabilities after cerebral ischemia." (PMID 31164999, 2019). "On one hand, IL-6 would further aggravate the deterioration of brain damage and counteract neural stem cell proliferation in the acute phase of cerebral ischemia." (PMID 31164999, 2019). "In this study, we demonstrated that cerebral ischemia-reperfusion injury caused elevated levels of TNF-α, IL-1β, and IL-6 in the serum." (PMID 31031621, 2019). "IL-6 KO mice subjected to brain ischemia exhibited an impaired angiogenic response with a reduced number of small vessels." (PMID 31814799, 2019). "Recently, it has been shown that cerebral ischemia can stimulate microglia and leukocyte to release inflammatory cytokine such as interleukin-6 (IL-6) which in turn increase the synthesis and release of C-reactive protein into the circulation." (PMID 29457029, 2017). "Activation of cell death pathways such as NF-κB and impairment of pro-survival signaling pathways are triggered by hypoxia, free radicals, and inflammatory mediators (Interleukin-1β and Interleukin-6) in cerebral ischemia." (PMID 28539998, 2017). "Our results showed that cerebral ischemia induced upregulation of IL-6, TNF-α, and IL-1β significantly, when compared with that of the control group." (PMID 28855861, 2017). "It has been well documented that inflammatory-associated cytokines such as IL-6 and TNF-α play a chief role in inflammatory activation upon cerebral ischemia-reperfusion injury." (PMID 28656054, 2017).